VEGFA (vascular endothelial growth factor A)
Diseases named in the same sentence as VEGFA in open-access papers (continued):
Sharing a sentence is not in itself a finding about the gene and the disease.
cancer (continued). "We identified ANGPT2 (logFC 3.9, FDR 2.00 × 10−4), APOA1(logFC −4.4, FDR 0.0067), FOS (logFC 1.4, FDR 0.0059) and VEGFA (z-score 2.228, overlap p-value 6.45 × 10−3) as the molecules of interest that have biomarker applications in various cancers." (PMID 35052372, 2021). "An integrated analysis of cancer and stroma transcriptome also detected putative paracrine signaling accelerators, such as the VEGFA, including a less-documented soluble factor, the APLN, in the KIRC pathology." (PMID 35079698, 2021). "Accordingly, cancer cells and stromal cells are able to produce and release mediators of angiogenesis, such as the vascular endothelial growth factor A (VEGF-A)." (PMID 33401382, 2021). "In this study, we found that a high level of VEGFA mRNA was carried by EVs derived from multiple types of cancer, and the level was modulated by the hypoxic stimulus." (PMID 33921957, 2021). "Bevacizumab is a monoclonal antibody against vascular endothelial growth factor‐A (VEGF‐A) and has already been applied to various cancer treatments." (PMID 33710778, 2021). "Taken together, these data suggest that cancer EVs carrying abundant VEGFA mRNAs can activate the VEGFA-VEGFR angiogenesis in endothelial vascular cells." (PMID 33921957, 2021). "Since MMP-9 and VEGFA have been implicated in the progression and metastasis of various cancers, western blot assessment was employed to measure the expression of MMP-9 and VEGFA in HCC cells treated with BJJP." (PMID 33762939, 2021). "Several anti-angiogenesis agents are currently used for cancer treatment, and act by targeting vascular endothelial growth factor A (VEGFA) and its receptors." (PMID 34298787, 2021). "Concomitantly, the cancer EVs induced VEGFA-dependent angiogenesis and upregulated epithelial-mesenchymal transition-related genes." (PMID 33921957, 2021). "In the PAF-AH 1B2 KD cancer cells’ enrichment pathways, the apoptotic signaling pathway and VEGFA-VEGFR2 signaling pathway, in particular, were highlighted and chosen for further investigation." (PMID 34930255, 2021). "MiR-424-5p target genes have been identified in various cancer types, including PD-L1, VEGFA, and ARK5." (PMID 33477683, 2021). "We verified the ubiquity of the EV-mRNAs derived from multiple cancer cell lines with the VEGFA mRNA as a candidate for proof-of-principle." (PMID 33921957, 2021). "Considering the striking therapeutic value of targeting NRPs for both models of cancers, we first analyzed the relative expression of NRPs and their ligands VEGFA and VEGFC on a panel of cell lines available in the TCGA data base." (PMID 33461580, 2021). "Understanding patient response to AAT treatment and the mechanisms of resistance has proved challenging as many cell types in the body (e.g., endothelial, immune, stromal, and cancer cells) are responsive to, for example, VEGFA signaling." (PMID 34267311, 2021). "Vascular endothelial growth factor A (VEGFA)-secreting macrophages promote the extravasation of cancer cells and lung metastasis." (PMID 34163472, 2021). "Ectopic expression of miR-375 significantly suppressed the expression of ERBB2 and subsequently downregulated one of its target genes, vascular endothelial growth factor A (VEGFA), which is related to cancer invasion and metastasis." (PMID 34729115, 2021). "Data showed that LINC00941 promoted cancer cells proliferation, while agomiR-877-3p or si-VEGFA reversed the accelerating effects of LINC00941 in NSCLC progression." (PMID 33869051, 2021). "In studies on human cancer cells inverse correlation of miR-185 and miR-200c to modulate VEGFA translation was found." (PMID 33670024, 2021). "As cancer cells become hypoxic, they induce an ‘angiogenic switch’ leading to expression of angiogenic factors including HIF1a, vascular endothelial growth factor A (VEGFA), PDGF, angiopoietin-2, pro-angiogenic chemokines and receptors." (PMID 34885021, 2021).
cancer (continued). "Because VEGFA is the master effector of the angiogenic response in cancers, we further examined the expression of VEGFA by Western blot and immunohistochemistry." (PMID 34948132, 2021). "Co-annotation of three pathway databases has shown that the miRNAs list is general in relation with pathways in cancer, VEGFA-VEGFR2 signaling pathway and PI3K-Akt signaling pathway." (PMID 35082831, 2021). "Bevacizumab, a monoclonal antibody against vascular endothelial growth factor-A (VEGF-A), has shown activity across cancers." (PMID 34036097, 2021). "And the inhibition of SRPK1 has been demonstrated to attenuate angiogenesis by altering VEGFA-165a to VEGFA-165b in cancer and kidney-related study." (PMID 34544400, 2021). "PDGFB, FN1, and VEGFA were the common genes involved in the regulation of cell adhesion, response to wounding, and pathways in cancer." (PMID 34606420, 2021). "Allows migration of cancer cells to distant organs through producing FSP1.Regulates angiogenesis through VEGFA." (PMID 35096289, 2021). "The best-known angiogenic regulators in cancer are vascular endothelial growth factor A (VEGF-A), von Willebrand factor (VWF), and thrombospondin-1 (TSP-1)." (PMID 33809480, 2021). "Fluorescent trafficking indicates cancer EVs deliver translatable mRNAs such as VEGFA to HUVECs, contributing to the activation of VEGFR-dependent angiogenesis and the upregulation of epithelial-mesenchymal transition-related and metabolism-related genes." (PMID 33921957, 2021). "Results from western blot and ELISA assays showed that PRMT3 overexpression promotes VEGFA expression of cancer cells." (PMID 34753906, 2021). "In the study which utilized the cancer-associated fibroblast (CAF)-endothelial cell co-culture model, hypoxic CAFs promoted angiogenesis through NCBP2-AS2-mediated vascular endothelial growth factor A (VEGFA) secretion." (PMID 32503591, 2020). "HIF-1α drives the expression of VEGFA, which controls cellular processes involved in cancer progression." (PMID 33081836, 2020). "That is, VEGFA causes autonomous proliferation itself via the AKT/PI3K/VEGFA pathway, which has previously been identified as an “autocrine VEGFA signaling loop” in numerous other cancers." (PMID 33692941, 2020). "In a chicken chorioallantoic membrane (CAM) assay, spliceostatin A reduced the expression of 38% of total genes (including VEGFA) and inhibited cancer cell-derived angiogenesis." (PMID 33287867, 2020). "Studies have shown that VEGFA/VEGFR2 is an important signaling axis in CRPC which allows the cancer cells to survive, proliferate and metastasize in an AR-independent manner." (PMID 32198489, 2020). "The involvement of Rho GTPases in modulating VEGFA signaling in both cancer cells and endothelial cells has also been well established." (PMID 32377503, 2020). "Vascular endothelial growth factor A (VEGF-A) is known to function directly in blood vessel formation and maintenance, and is a promising therapeutic target for activation in cancer." (PMID 31850493, 2020). "Expression of genes that played a pivotal role in cancer cell migration, including VEGFA, PLAU, MMP2, MMP9, and MMP14, were reduced in dose-dependent manner of stigmasterol in both cell lines." (PMID 32481565, 2020). "MMPs and VEGFA are the most critical prometastatic and proangiogenic factors that inhibit cancer cell apoptosis, decrease cell adhesion, and induce angiogenesis, resulting in the promotion of the development and progression of CRC." (PMID 32258125, 2020). "VEGF-A (vascular endothelial growth factor-A) is a key regulator of angiogenesis and is widely up-regulated in numerous cancers, BC being one of them." (PMID 33143050, 2020). "miR-205 modulates the expression of AKT and VEGFA signaling pathways, and as a result, regulates cellular proliferation, cell cycle, and apoptosis in a variety of cancers." (PMID 32854238, 2020). "VEGFA is a protein that induces the formation of new blood vessels and is often upregulated in the majority of cancers." (PMID 32854238, 2020).
cancer (continued). "TRPV1 had a negative relationship with the well-recognized cancer suppressor gene Pten and a positive relation with VEGFA, a known cancer promoting gene." (PMID 32913462, 2020). "This binding resulted in the expression of several target genes involved in angiogenesis, proliferation, migration and invasion of cancer cells, such as VEGFA, EGFR, c-Myc, Cyclin D1 and MET." (PMID 33088626, 2020). "In the absence of PTEN, HIF-1α is able to act as a transcription factor for VEGFA, increasing angiogenesis, as well as activating other pathways that promote aggressive cancer phenotypes." (PMID 32707933, 2020). "Among them, genes such as BCL2, CSNK2A1, EGFR, PDGFRA, VEGFA, etc., which have been proved to be targets of anti-cancer drugs, were proposed to provide general administrations for pan-cancers." (PMID 32523951, 2020). "These novel findings define the mechanism of KSHV induction of the SPAG9/JNK/VEGFA pathway and establish the scientific basis for targeting this pathway for treating KSHV-associated cancers." (PMID 32776977, 2020). "In return, hypoxic cancer cells release angiogenesis-inducing factors, mainly vascular endothelial growth factor A (VEGF-A), which engages VEGFR2 expressed by endothelial cells (ECs)." (PMID 31256327, 2020). "miR-622 is upregulated in nCRT responders with a parallel decrease in VEGFA expression leading to a decreased endothelial cell proliferation with a consequent reduction in new blood vessel formation, feeding cancer mass." (PMID 32580435, 2020). "In receiver operating characteristic (ROC) analyses, the hazard model based on a triple-negative cancer phenotype variable, combined with specific SNPs in VEGFA (rs833061), VEGFR1 (rs9582036) and VEGFR2 (rs1870377), had the highest predictive value." (PMID 33238394, 2020). "Both macrophages and cancer cells increase the production of angiotropic cytokines, vascular endothelial growth factor-A (VEGF-A), platelet-derived growth factor (PDGF), and transforming growth factor-β TGF-β." (PMID 32630815, 2020). "VEGFA is considered to be one of the important drivers of cancer angiogenesis and reported to related with increasing of vascular distribution, metastasis and leading to the poor prognosis of some cancers." (PMID 32756011, 2020). "For example, in urologic cancer, common genes regulated by prognosis-alternative miRNAs such as BCL2, EGFR, KIT, PDGFRA, and VEGFA, have been validated as anti-cancer drug targets previously." (PMID 32523951, 2020). "Uncontrollably, VEGFA secretion accelerates the malignant changes of cancer under hypoxia or heat stimulation." (PMID 33145353, 2020). "The inhibition of this switching loop together with the significant reduction in endothelial marker expression and HBMEC migration was only reached when high VEGFA cancer cell lines were treated with the specific dose." (PMID 32564774, 2020). "Altogether, these findings suggest that VEGFA SNPs are B-CLL susceptibility markers, as has been described in other cancers." (PMID 32585853, 2020). "In the minimum protein–protein network and enrichment analysis, genes from amphicrine carcinoma were mostly related to VEGFA node and pathways in cancer." (PMID 31832022, 2019). "Agents that selectively target VEGFA, its receptor or its downstream signaling pathway effectively improve the survival rates of patients with a variety of cancers." (PMID 31023336, 2019). "Several proteins are closely related to the migration and invasion of cancers, such as VEGFA, MMP2, and MMP9." (PMID 31631580, 2019). "Together, these data show that the stimulation of cancer cell angiogenesis by EHD1 is highly dependent on VEGFA." (PMID 31023336, 2019). "Angiogenesis is vital for the development of cancer and metastasis; the chief proangiogenic factor in these processes is vascular endothelial growth factor-A (VEGF-A)." (PMID 31809267, 2019).
cancer (continued). "Upregulation of VEGFA indicates neoangiogenesis, low-differentiation and progression in cancer cells, whereas VEGFD plays a key role in neovascularization and formation of lymphatic vessels in cancer tissues." (PMID 31073526, 2019). "Given that VEGFA was crucial for cancer growth and neovascularization, we examined the expression of VEGFA in SMMC‐7721 and HCC‐LM3 cells overexpressing EYA4 or vector." (PMID 30957411, 2019). "For this reason, the inhibition of the binding of VEGFA with VEGFR‐2 is the goal‐target for biological cancer therapies." (PMID 31369203, 2019). "Possibly due to the variety of cut-off value of PD-L1 and VEGFA positive expression in cancer, results of our study are different with that from previous some studies (positive PD-L1 ever defined as 1, 5, 10, or even 50%)." (PMID 30972298, 2019). "FLT1, a tyrosine kinase receptor, acts as a promoter in cancer growth and metastasis, whose affinity with VEGFA is approximately ten times higher than KDR." (PMID 31383782, 2019). "The epithelial-mesenchymal transition effect of VEGFA is also verified in cancer and retinal pigment epithelial cells." (PMID 31488217, 2019). "This is a widespread cancer-related phenomenon known as the Warburg effect, which was followed by an increase in vascular endothelial growth factor A (VEGFA) expression." (PMID 29649101, 2018). "Genetic inactivation of STAT5, which is necessary for NK cell-mediated cancer immunosurveillance, increases VEGFA in NK cells and stimulates angiogenesis in mouse lymphoma models and on healthy donor-derived NK cells." (PMID 29675018, 2018). "Increased permeability of the pulmonary endothelium in the 3rd week after cancer cell inoculation correlated with a transient increase in VEGFA and VCAM-1 expression in the lungs." (PMID 30075800, 2018). "VEGFA is also the chief exciter of both endothelial progenitor cells (EPCs) and endothelial cells (ECs) in cancer patients as well as in healthy individuals." (PMID 30622613, 2018). "VEGFA is a potent angiogenic growth factor, commonly involved in the pathogenesis and progression of various cancers." (PMID 29263143, 2018). "A number of cancer-associated genes were found, including TGIF1, VEGFA, RUNX1, and PIM1, as well as others." (PMID 29641996, 2018). "The gene VEGF encodes vascular endothelial growth factor A (a potent angiogenic factor) and agents that inhibit VEGF are in clinical use for cancer." (PMID 30423844, 2018). "One of the mechanisms responsible for VEGFA expression in both physiologically normal and cancer cells is transforming growth factor-β (TGF-β) stimulation." (PMID 28008154, 2017). "Inappropriate angiogenesis is a key factor in a range of conditions including cancer and proliferative eye diseases; blockade of VEGFA signalling to inhibit angiogenesis and reduce vascular leakage forms the basis of multiple effective clinical treatments." (PMID 28246395, 2017). "Here, we showed that ADAM9 also contributes the functions of angiogenesis and vascular remodeling for cancer progression through regulation of VEGFA, ANGPT2, and PLAT via in vitro and in vivo experiments." (PMID 29118335, 2017). "Regardless of clinicopathological characteristics, significant expression differences were observed, including 10 upregulated genes (CCL4/18, CXCL1/10/11, IFNγ, IL2/6/12A, VEGFA) and 1 downregulated gene (HLA-A) in lymphocytes from malignant ascites." (PMID 28620375, 2017). "VEGFA stimulates the growth of the vascular network that supports cancer growth and metastasis and is often up-regulated in cancers." (PMID 29137669, 2017). "Unlike JSRV-induced adenocarcinomas, mRNA and proteins of VEGFA were expressed in human lepidic adenocarcinomas but at very low levels in cancers and in their normal counterparts." (PMID 29137669, 2017).
cancer (continued). "TEAD can also interact with multiple other coactivators that play an important role in cancer progression, such as Vgll proteins that upregulate the expression of VEGFA gene, the pro-angiogenic factor involved in cancer pathogenesis." (PMID 28790340, 2017). "In breast lines and primary cancer culture, VEGFA rapidly upregulates SOX2 expression, leading to SNAI2 induction, EMT, increased invasion and metastasis." (PMID 28504716, 2017). "VEGFA, whose expression is induced in hypoxia, would support both angiogenesis and expansion of stem‐like cancer cells." (PMID 28179359, 2017). "The importance of VEGFA in angiogenesis and its frequent upregulation in human cancers stimulated development of VEGF‐ and VEGF receptor‐targeted therapies." (PMID 28179359, 2017). "The mRNA expression of VEGFR2, the main receptor of VEGFA, was significantly reduced in cancers as compared to normal lungs and undetectable in AECII cultures derived from cancers or normal lungs." (PMID 29137669, 2017). "We analyzed the levels of mRNA expression of VEGFA using RT-qPCR and its protein expression by Western blot in normal lungs, cancers, and lung-derived AECII cultures." (PMID 29137669, 2017). "While VEGFA, B, C and D are secreted by cancer cells, their receptors VEGFR1, R2 and R3 are expressed at the surface of endothelial cells." (PMID 29137669, 2017). "VEGFA can also stimulate stem‐like cells in certain cancers, but mechanisms thereof are poorly understood." (PMID 28179359, 2017). "VEGFA is the main inducer of angiogenesis and proliferation and migration of cancer cells; thereby the VEGFA/VEGFR2 complex is a key player for the activation of angiogenesis." (PMID 29137669, 2017). "The local acidified environment can facilitate cancer invasion via an increase in vascular endothelial growth factor A (VEGFA)." (PMID 28915713, 2017). "In pathway in cancer, we found that Bcl2, VEGFA, PTEN, Jun, Fos, APC2 gene expression were up-regulated and the expression of Myc was down-regulated in the MMQ TSLCs." (PMID 28163656, 2017). "VEGFA is not only a potent angiogenic factor, it also stimulates stem‐like cells in both normal and cancer tissues." (PMID 28179359, 2017). "SNPs in VEGFA are involved in several types of cancers, such as the bladder, esophageal, thyroid and gastric cancers." (PMID 28178662, 2017). "Analysis of carcinoma cells in animals showed bcl‐2, Ki67, VEGFA, CD24 and CD44 expression decrease and Bax, caspase‐3 and ALDH1 expression increase after high‐dose CLO administration." (PMID 28524540, 2017). "We found that the VEGFA enhancer was significantly hypomethylated in all the examined cancer types (left)." (PMID 26886256, 2016). "We explored the relationships between methylation of the VEGFA enhancer site and expression of the VEGFA oncogene across cancer types and patients." (PMID 26886256, 2016). "Inhibition of EGFR signaling has also been shown to decrease the production of VEGFA in cancer cells." (PMID 27941682, 2016). "We found that cancers displaying a high percentage of ZEB1-positive cells exhibited a high level of VEGFA expression and CD31 density." (PMID 26882471, 2016). "Further analyses of a hypomethylated ESSE downstream to the VEGFA gene revealed a novel regulatory circuit affecting VEGFA transcript levels across cancers and patients." (PMID 26886256, 2016). "The aim of the current study was to examine the consequence of specific suppression of VEGFA-induced permeability on cancer progression." (PMID 27005951, 2016). "Another gene in the instrument (VEGFA) is targeted by monoclonal antibody therapeutics or an aptamer used to block angiogenesis in the treatment of certain cancers and age-related macular disease." (PMID 26781229, 2016). "However, the mechanism underlying VEGFA activation in cancers is unknown." (PMID 26886256, 2016).